GRM7 (glutamate metabotropic receptor 7)
Description:
G protein-coupled receptor activated by glutamate that regulates axon outgrowth through the MAPK-cAMP-PKA signaling pathway during neuronal development. Ligand binding causes a conformation change that triggers signaling via guanine nucleotide-binding proteins (G proteins) and modulates the activity of downstream effectors, such as adenylate cyclase that it inhibits.
Synonyms: mGluR7; GPRC1G; GLUR7; mGlu7; PPP1R87; NEDSHBA
Tractability: Small molecule: a structure with a bound ligand is known; a high-quality ligand is known; it has a high-quality binding pocket; it belongs to a druggable protein family. Antibody: UniProt places it where antibodies can reach, with high confidence; its Gene Ontology location is reachable by antibodies, with high confidence; UniProt predicts a signal peptide or a membrane-spanning region. PROTAC: its protein half-life has been measured; a small molecule that binds it is known.
Target class: Family C G protein-coupled receptor; Metabotropic glutamate receptor; Small molecule receptor (family C GPCR); Membrane receptor; Neurotransmitter receptor (family C GPCR)
Chemical probes: VU 0422288, VU0155094
Gene: Protein-coding gene on chromosome 3 (6,770,001 to 7,741,533, forward strand). Ensembl gene ENSG00000196277.
Subcellular location: Cell membrane
Subcellular location (Human Protein Atlas): Cytosol
Pathways (Reactome):
Signal Transduction: Class C/3 (Metabotropic glutamate/pheromone receptors); G alpha (i) signalling events
Gene Ontology:
Molecular function: adenylate cyclase inhibitor activity; glutamate receptor activity; group III metabotropic glutamate receptor activity; protein dimerization activity; serine binding; calcium channel regulator activity; G protein-coupled receptor activity; voltage-gated calcium channel activity
Biological process: adenylate cyclase-inhibiting G protein-coupled glutamate receptor signaling pathway; axon development; behavioral fear response; chemical synaptic transmission; sensory perception of sound; G protein-coupled glutamate receptor signaling pathway; negative regulation of glutamate secretion; regulation of synaptic transmission, glutamatergic; calcium ion transmembrane transport; G protein-coupled receptor signaling pathway; presynaptic modulation of chemical synaptic transmission
Cellular component: cell cortex; dendrite; membrane; plasma membrane; receptor complex; asymmetric synapse; axon; dendritic shaft; postsynaptic membrane; presynaptic active zone; glutamatergic synapse; presynaptic membrane
Genetic constraint (gnomAD): Loss-of-function variants: 30 observed, 74.06 expected, observed/expected ratio (o/e) 0.41, 90% interval 0.3 to 0.55. The upper end of that interval is the gene's LOEUF score, 0.55, which puts it in group 2 of 6, group 1 being the genes least tolerant of losing a copy. Missense variants: 948 observed, 1,164.8 expected, observed/expected ratio (o/e) 0.81, 90% interval 0.77 to 0.86. Synonymous variants: 460 observed, 449.04 expected, observed/expected ratio (o/e) 1.02, 90% interval 0.95 to 1.11.
Homologues: Orthologues: macaque GRM7 (99% identical), chimpanzee GRM7 (98% identical), dog GRM7 (98% identical), pig GRM7 (98% identical), mouse Grm7 (98% identical), rat Grm7 (98% identical), guinea pig GRM7 (97% identical), tropical clawed frog grm7 (84% identical), rabbit GRM7 (70% identical), zebrafish GRM7 (58% identical), Drosophila melanogaster mGluR (46% identical). Paralogues in human: GRM8 (73% identical), GRM4 (68% identical), GRM6 (63% identical), GRM3 (43% identical), GRM2 (42% identical), GRM5 (40% identical), GRM1 (40% identical).
Diseases named in the same sentence as GRM7 in open-access papers:
GRM7 is named in the same sentence as 67 diseases in open-access papers, as found by Europe PMC text mining. Sharing a sentence is not in itself a finding about the gene and the disease. The quoted sentences say what the papers report.
schizophrenia (32 papers, 2010 to 2025). A major psychotic disorder characterized by abnormalities in the perception or expression of reality. "Additional SNPs of GRM7 (rs141134664, rs57521140, and rs73809055) are associated with risperidone treatment outcomes in a schizophrenia GWAS." (PMID 40149928, 2025). "Further studies on schizophrenia with polymorphisms in GRM7 identified two neighboring SNPs (rs12491620 and rs1450099) in GRM7, showing a highly significant haplotype association." (PMID 40149928, 2025). "Genetic variants in the gene encoding the mGluR7 (GRM7) have also been shown to be associated with schizophrenia." (PMID 39858450, 2025). "The mGlu7 is considered a therapeutic target for several psychiatric and neurological disorders, and GRM7 polymorphisms have been linked to schizophrenia, depression, autism, and ADHD." (PMID 36980845, 2023). "With regard to the core risk factors, the GRM7 gene is significantly correlated with the schizophrenia patients." (PMID 32127521, 2020). "In the Japanese population, some of these loci (MHC region, CSMD1, GRM7) have been associated with schizophrenia but the majority of current candidate loci have yet to be fully characterized." (PMID 28855529, 2017). "In human, GRM7 gene polymorphisms have recently been associated with autism, schizophrenia, attention deficits and hyperactivity, age-dependent auditive deficits, although not yet to epilepsies." (PMID 27199672, 2016). "It is highly significant in both LS and mPFC arrays, while other glutamate-related genes strongly linked to schizophrenia, such as the kainate receptor 3 (Grik3), and metabotropic glutamate receptors 5 and 7 (Grm5, and Grm7), are only significant in mPFC." (PMID 24765068, 2014). "Hence our research elucidates that GRM7 variants play the critical role of predicting the risk of schizophrenia and antipsychotic effect of seven common drugs." (PMID 32127521, 2020). "In summary, this study furtherly proved GRM7 as the risk factor of schizophrenia." (PMID 32127521, 2020). "A polymorphism in the GRM7 gene encoding mGlu7 that reduced transcription in vitro was found to be positively associated with schizophrenia in a large Japanese cohort, indicating that hypofunction of mGlu7 may contribute to this disorder." (PMID 28446243, 2017). "GRM7 analysis in a population of Japanese schizophrenics identified a single nucleotide polymorphism (SNP) with lower promoter activity, suggesting that lower expression of mGluR7 may increase the risk of developing schizophrenia." (PMID 22942876, 2012). "In cultured cell lines, mood stabilizers could both lower the levels of miR-34a and elevate the levels of GRM7, a confirmed target gene regulated by miR-34a as well as a candidate gene for schizophrenia identified in recent association studies." (PMID 21738743, 2011). "Approximately 60% of the observed decreases in 5mC occurred in the promoter regions of genes, including schizophrenia susceptibility genes such as GAD1 and glutamate metabotropic receptor 7 (GRM7)." (PMID 38203806, 2024). "We examined the association of 39 single nucleotide polymorphisms in eight genes (GRIN2A, GRIN2B, SLC1A2, SLC1A3, SLC17A7, GRM3, GRM7, and GRM8) involved in the glutamatergic system with the development of clinical heterogeneity of schizophrenia." (PMID 36980845, 2023). "Rs2133450 is in the glutamate metabotropic receptor GRM7 and rs1875705 in the NMDA receptor subunit GRID2, likely modulating glutamatergic neurotransmission, whose dysfunction contributes to schizophrenia." (PMID 38523642, 2024). "On the whole, findings from the GWAS and the WES can build up a pathway network where the GRM7 is the central hub gene and the GPCR signaling pathway may be the main signal transduction pathway in pathophysiology of schizophrenia and response to risperidone." (PMID 35484098, 2022).
schizophrenia (continued). "Among these 16 SZGenes, several (DRD2, GRIN1, GRM7 and GAD1) are related to three neurochemical hypotheses in the molecular mechanisms of schizophrenia, i.e., the dopamine, glutamatergic and GABAergic hypotheses." (PMID 20156358, 2010).
Anxiety (18 papers, 2013 to 2026). Intense feelings of nervousness, tension, or panic often arise in response to interpersonal stresses. "Recently it has also been demonstrated that 3xTg-AD mice showed lower GRM7 protein expression in hippocampus, associated with an increased anxiety behavior, compared with the wild-type mice." (PMID 32694537, 2020). "An association between GRM7 and anxiety has been previously reported." (PMID 23295062, 2013). "The amygdala and hippocampus in the brain are known to play a key role in alleviating anxiety and antidepressant, and GRM7 is abundant in these regions." (PMID 36597080, 2023). "Thus, GRM7 may be involved in the regulatory circuit that affects anxiety and/or depressive behavior." (PMID 36597080, 2023).
epilepsy (14 papers, 2013 to 2026). A brain disorder characterized by episodes of abnormally increased neuronal discharge resulting in transient episodes of sensory or motor neurological dysfunction, or psychic dysfunction. "Early studies on ADHD pointed to GRM7, and later, in ADHD and epilepsy, the interaction of mGlu7-Elfn1 has been implicated (Elfn1 is clustered in the carboxy-terminal region required for mGluR7 recruitment)." (PMID 40149928, 2025). "Here, we present new clinical cases of 2 sisters with severe developmental delay and epilepsy confirmed to be homozygous for a GRM7 variant c.461T>C p.Ile154Thr (mGlu7-I154T)." (PMID 33476302, 2021). "Of note, ELFN1 mutations clustered in the region required for mGlu7 recruitment have been found in patients with epilepsy and ADHD, and ELFN1 knockout (Elfn1-/-) animals exhibit a similar seizure phenotype to Grm7-/- animals." (PMID 30405350, 2018). "Two genes among them were included in curated epilepsy genes, and we could find compound heterozygous variants of GRM7, c.589C>T (p.Arg197Cys), and c.1972C>T (p.Arg658Trp), and a hemizygous splicing variant of SHROOM4 (c.269+4A>G)." (PMID 35937050, 2022). "Therefore, loss-of-expression or loss-of-function mutations in GRM7 should be considered as a potential underlying cause for patients with unexplained developmental delay and epilepsy." (PMID 33476302, 2021). "A previous study reported that GRM7 plays a role in neurologic diseases such as depression, epilepsy and bipolar disorder, regulating synaptic activity." (PMID 34204705, 2021). "mGluR7‐knockout mice develop spontaneous stimulus‐provoked seizures, suggesting that disruption of GRM7 expression may cause epilepsy." (PMID 32286009, 2020). "In addition, the reduced expression of Grm7 and Grm8 that we found in all studied regions may also contribute to epilepsy development." (PMID 35269897, 2022). "Additionally, the mediumblue module (Pvalb subtypes, 173 genes), while not passing the test for associating more strongly with epilepsy than with any sample, included the genes GRIK1, GRIK2, GRIK4, GRM1, GRM7, and GRIA1, suggesting a potential involvement in glutamate receptor subunits." (PMID 33028830, 2020).
depression (13 papers, 2013 to 2025). "In this study, we explored the association between SNPs of candidate genes CREB1 and GRM7 in depression among Chinese people." (PMID 36597080, 2023). "With regard to depression, a meta-analysis showed that the rs162209 polymorphism in the GRM7 gene was closely associated with depression." (PMID 36597080, 2023). "GRM7 variants have shown allelic associations with depression in several studies." (PMID 40149928, 2025). "The purpose of this study was to investigate whether the CREB1 polymorphisms rs2253206 and rs10932201 and the GRM7 polymorphism rs162209 are associated with the risk of depression." (PMID 36597080, 2023). "However, other studies have reported that GRM7 is associated with depression, and Genome-wide association study (GWAS) and meta-analyses have also shown that GRM7 is associated with depression." (PMID 36597080, 2023). "However, there are few reports on the genetic susceptibility of CREB1 SNPs rs2253206 and rs10932201 and GRM7 SNPs rs162209 involved in depression." (PMID 36597080, 2023). "Likewise, metabotropic glutamate receptor 7 (GRM7) encodes the protein mGluR7 mediates the glutamate neurotransmission, found to be involved in the development of the major depressive disorder." (PMID 31018568, 2019). "GRM7 codes for the metabotropic glutamate receptor 7 and an intronic SNP in this gene showed a P-value that approximated genome-wide significance in a meta-analysis of three depression cohorts." (PMID 24278217, 2013). "In order to verify their correlation with depression and explore their possible mechanisms, we investigated the association of the CREB1 SNPs rs2253206 and rs10932201 and the GRM7 rs162209 with first onset, family history, and suicidal tendency in patients with depression." (PMID 36597080, 2023). "Previous work has shown that the rs2253206 and rs10932201 in CREB1 and rs162209 in GRM7 may light on the pathogenesis of depression." (PMID 36597080, 2023). "Other studies could not confirm an association between the GRM7 polymorphism rs162209 and depression in 479 patients with depression and 329 normal controls." (PMID 40149928, 2025). "Apart from CREB1, metabotropic glutamate receptor 7 (GRM7), which mediates the effect of glutamate on neurotransmitter release and cell excitability, has been found to be related to depression." (PMID 36597080, 2023). "In 2010, a study reported that the SNP rs162209 in the GRM7 gene was related to depression, but there have been no subsequent reports on the role of this SNP in depression." (PMID 36597080, 2023).
attention deficit-hyperactivity disorder (11 papers, 2013 to 2025). A disorder characterized by a marked pattern of inattention and/or hyperactivity-impulsivity that is inconsistent with developmental level and clearly interferes with functioning in at least two settings (e.g. at home and at school). "In humans, GRM7 is associated with developmental brain defects, such as attention deficit hyperactivity disorder and autism." (PMID 41146205, 2025). "This association is supported by the identification of GRM7 variants in patients with autism spectrum disorder, attention deficit hyperactivity disorder, and severe developmental delay." (PMID 33476302, 2021). "Metabotropic glutamate receptor 7 (GRM7) has been linked to brain developmental defects, such as attention deficit hyperactivity disorder (ADHD)." (PMID 32850847, 2020). "GRM6 and GRM8, the paralogs of GRM7, have been implicated in neurodevelopmental diseases such as attention deficit hyperactivity disorder (ADHD) and autism spectrum disorders (ASD)." (PMID 27435318, 2016). "Interestingly,individuals with mutations in ELFN1 or GRM7 genes present with attention-deficit hyperactivity disorder andepilepsy, and knockout mice of each of these proteins develop seizureswith very similar time courses." (PMID 40689847, 2025). "One more study has established an association between the metabotropic glutamate receptor 7 (GRM7) and brain developmental disorders such as attention deficit hyperactivity disorder (ADHD) and autism." (PMID 39936032, 2025). "In addition to a gain of the NPY gene in a familial case with EOO and attention deficit hyperactivity disorder, likely pathogenic CNVs included gains of glutamate receptors (GRIK1, GRM7) and the X-linked gastrin-peptide receptor (GRPR), all inherited from obese parents." (PMID 28489853, 2017).
autism (9 papers, 2011 to 2025). Persistent deficits in social interaction and communication and interaction as well as a markedly restricted repertoire of activity and interest as well as repetitive patterns of behavior. "mGluR7 is encoded by Grm7 gene, a known autism-linked gene whose truncation and missense mutations have been associated with idiopathic autism and developmental delay." (PMID 38374465, 2024). "There is prior evidences that GRM7 impact specific brain function associated with spatial learning, memory, understanding of speech, and autism in humans." (PMID 25765548, 2015).
age-related hearing loss (8 papers, 2013 to 2023). "Several independent studies have reported that the gene encoding glutamate metabotropic receptor 7 (GRM7) is associated with presbycusis." (PMID 37727326, 2023). "For both genders, the T allele in GRM7 gene is the most common allele in our sample of older adults with presbycusis and tinnitus, where genotypes A/T and T/T present higher level of hearing loss compared to A/A genotype." (PMID 29163129, 2017). "Mutations in GRM7 may lead to the accumulation of neurotransmitters in synaptic connections, thereby altering the susceptibility to presbycusis." (PMID 37727326, 2023). "Furthermore, a closely related gene (Grm7) has been reported to be associated with age-related hearing loss." (PMID 31927188, 2020). "In addition to the neuropsychiatric phenotypes, GRM7 has been linked to age-related hearing loss and impairment in several studies." (PMID 30655508, 2019). "Perhaps in a larger population it could be demonstrated that the allele A of GRM7 plays a protective role in presbycusis." (PMID 29163129, 2017). "Despite recent progress, almost nothing is known about the molecular bases of variation of normal hearing, apart from genes identified as being directly involved in hereditary hearing loss and one gene (GRM7) recently described associated with age-related hearing loss (ARHL) in humans." (PMID 24454846, 2014).
hearing loss (8 papers, 2012 to 2025). "Studies have shown that genetic variation in GRM7 is likely associated with the development of ARHL and invisible hearing loss and that the overexpression of GRM7 may lead to the inhibition of neurotransmission between hair cells and synapses." (PMID 39411148, 2024). "Up to now, when it comes to GRM7, previous studies have shown that GRM7 polymorphisms are associated with the susceptibility to hearing loss in the elderly, but the relationship between GRM7 polymorphisms and NIHL susceptibility remains to be further validated." (PMID 29301492, 2018). "Variants of genes GRM7, ISG20, TRIOBP, ILDR1, and EYA4 have shown significant associations with hearing loss and highlight the need to disentangle the genetic architecture of ARHL and standardize phenotyping methods for facilitating data sharing and collaboration across research networks." (PMID 40149928, 2025).
bipolar disorder (5 papers, 2011 to 2025). A disorder of the brain that causes unusual shifts in mood, energy, activity levels and the ability to carry out day-to-day tasks. "In a second sample of 593 patients and 642 controls (UCL2) the association between GRM7 and bipolar disorder (BP) could be confirmed." (PMID 40149928, 2025).
developmental delay (5 papers, 2018 to 2025). "We have identified a family from Saudi Arabia in which the recessive GRM7 variant c.461T>C p.Ile154Thr segregates with severe developmental delay." (PMID 33476302, 2021). "Genetic studies linking GRM7 to other NDDs (such as ASD, MS, and specific GRM7 mutations associated with brain atrophy and hypomyelination, intellectual disability, developmental delay, autism spectrum disorder, and seizures) have recently been reviewed in detail." (PMID 40149928, 2025).
glioma (4 papers, 2009 to 2025). A benign or malignant brain and spinal cord tumor that arises from glial cells (astrocytes, oligodendrocytes, ependymal cells). "GRM7 is one of a subset of genes that predict a positive prognosis in low-grade gliomas and a negative prognosis in GBM, showing progressive downregulation across glioma grades implicating GRM7 in cancer progression." (PMID 40149928, 2025). "Specially, the expression level of GRM7 was validated in human glioma cell line U251." (PMID 30124166, 2018). "Specially, the present study used real-time PCR to verify the expression of key genes GRM2, GRM7, HTR2A and TFAP2C through human glioma cell line U251." (PMID 30124166, 2018).